SOD1 (superoxide dismutase 1)
Diseases named in the same sentence as SOD1 in open-access papers (continued):
Sharing a sentence is not in itself a finding about the gene and the disease.
Age-related cataract (8 papers, 2016 to 2025). A type of cataract (opacification of the lens) that forms during the course of aging. "A previous study from our group found that the decrease of histone acetylation at the SOD1 promoter is associated with the decrease of SOD1 expression in age-related cataracts." (PMID 30717701, 2019). "Decreased histone acetylation at the SOD1 promoter is associated with declined SOD1 expression in senile cataracts." (PMID 27703255, 2016). "Both superoxide dismutase and catalase have been implicated in age-related cataracts, emphasizing the importance of this pathway for lens homeostasis, even though levels of superoxide dismutase 1, the cytoplasmic form implicated in age-related cataracts, is relatively low in the lens." (PMID 39594457, 2024). "This confirms that histone acetylation plays an important role in regulating SOD1 expression and the pathogenesis of age-related cataracts." (PMID 37759978, 2023). "In age-related cataracts, histone 3 and histone 4 undergo deacetylation at −600 bp of the SOD1 promoter in the cataract lens, with low acetylation at −1500, −1200, and −900 bp." (PMID 37759978, 2023). "Histone acetylation has an important role in regulating SOD1 expression which participate in the pathogenesis of age-related cataracts." (PMID 30717701, 2019). "Histone acetylation plays an essential role in the regulation of SOD1 expression and in the pathogenesis of senile cataracts." (PMID 27703255, 2016). "The results showed that both H3 and H4 were deacetylated at −600 bp of SOD1 promoter in the LE of senile cataracts." (PMID 27703255, 2016). "In conclusion, H3 and H4 acetylation decreased significantly at the SOD1 promoter in senile cataracts." (PMID 27703255, 2016). "The regulation of histone acetylation on SOD1 expression plays an essential role in the pathogenesis of senile cataracts." (PMID 27703255, 2016). "The aim of the present study was to explore differences in histone acetylation modification at the SOD1 promoter region between normal transparent lenses and senile cataracts." (PMID 27703255, 2016). "The results provided evidence that histone acetylation plays an important role in regulating SOD1 expression and in the pathogenesis of senile cataracts." (PMID 27703255, 2016). "In senile cataracts, SOD1 expression decreased significantly." (PMID 27703255, 2016). "Thus, the present study was designed to explore histone acetylation and SOD1 expression changes in the lens epithelia of senile cataract cases and to illustrate the regulation effects of histone acetylation modification on SOD1 gene expression in the pathogenesis of senile cataracts." (PMID 27703255, 2016). "For example, although histone acetylation changes were detected at −1500~0 bp of the SOD1 promoter region in senile cataracts, the exact acetylated sites in the histones were not determined." (PMID 27703255, 2016).
co-infection (8 papers, 2015 to 2024). "Distinctly, VL1 patient, that has disorganized spleen and VL-HIV coinfection was related to SOD1, STAT3, STAT4, ICOS, TRAF6 and IRF3 genes, and CD8+ cells in the RP and expression of IL6 in both regions of spleen." (PMID 38843306, 2024).
diabetic neuropathy (8 papers, 2010 to 2025). A chronic, pathological complication associated with diabetes mellitus, where nerve damages are incurred due to diabetic microvascular injury involving small blood vessels that supply these nerves, resulting in peripheral and/or autonomic nerve dysfunction. "We chose two distinct models to test our hypothesis: 1) the leptin receptor deficient mouse (dbdb) model of diabetic polyneuropathy and 2) superoxide dismutase 1 knockout (Sod1−/−) mouse model of in vivo oxidative stress." (PMID 23750273, 2013). "We chose two distinct models to address the questions, the well-characterized leptin receptor deficient (dbdb) mouse model of diabetic polyneuropathy, and mice lacking the superoxide dismutase 1 (Sod1) gene (Sod1−/−) as a model of in vivo oxidative stress." (PMID 23750273, 2013). "Thus, examining the SOD1 KO mouse as a model of diabetic neuropathy would be a reasonable follow-up study." (PMID 20979611, 2010).
dry eye (8 papers, 2014 to 2024). "Animal models with increased oxidative stress, such as SOD-1 deficient mice, have also been reported to cause abnormalities in the lacrimal glands and meibomian glands, causing dry eye." (PMID 36313100, 2022). "Furthermore, Dogru and colleagues reported that Sod1−/− mice also exhibited typical dry eye associated with lacrimal gland and meibomian gland changes, and this occurred in an age-dependent manner." (PMID 25276767, 2014). "In the results of the dry eye syndrome group, we also observed an increase in SOD1, responsible for 90% of SOD antioxidant activity." (PMID 38254630, 2023). "It has been reported that dry eye phenotypes appear in aged SOD1 knockout mice." (PMID 28203523, 2016).
hearing loss (8 papers, 2010 to 2025). "Notably, previous research has demonstrated that decreased SOD1 expression, which likely exacerbates oxidative stress, increases vulnerability to noise‐induced hearing loss and age‐related hearing loss." (PMID 39049179, 2024). "Thus, altered Sod1 expression in DKO mice suggests elevated oxidative stress contributes not only to overt hearing loss but also hidden hearing loss and, moreover, that increased Sod1 expression is insufficient in protecting against hidden and subsequent overt hearing loss." (PMID 39049179, 2024). "Interestingly, polymorphisms in the gene encoding catalase have been linked to an increased susceptibility to hearing loss in humans, and mice that are heterozygous for a mutation in Sod1 gene show an increased vulnerability to hearing loss induced by noise exposure." (PMID 30090654, 2018). "However, it has also been shown that overexpression of SOD1 does not confer protection against hearing loss." (PMID 39049179, 2024). "Furthermore, several mouse lines, which were deficient for antioxidant components, such as superoxide dismutase 1 (SOD1), glutathione peroxidase 1(GPX1), plasma membrane calcium ATPase 2(PMCA2) or Cadherin Related 23 (CDH23) showed also increased sensitivity to noise-induced hearing loss." (PMID 38397817, 2024).
iron deficiency (8 papers, 2018 to 2025). "Iron deficiency resulted in a lower protein expression of SOD2 (Mn-SOD) and higher SOD3 (extracellular Cu/Zn-SOD), whereas a decreasing trend in SOD1 (intracellular Cu/Zn-SOD) was observed." (PMID 35631204, 2022).
migraine (8 papers, 2019 to 2025). "Here, we confirm our previous findings and, for the first time to our knowledge, demonstrate that the LTA rs2071590 T allele (OR = 2.2) and the SOD1 rs2234694 C allele (OR = 4.9) were both associated with MRI findings of WMHs in migraine patients." (PMID 36430258, 2022). "SNP analysis of observed allele and genotype frequencies demonstrated that the LTA rs2071590 T allele (OR = 2.2; p = 0.034) and the SOD1 rs2234694 C allele (OR = 4.9; p = 0.003) were both associated with MRI findings of WMHs in inheritance models of migraine patients." (PMID 36430258, 2022). "This hypothesis is corroborated by the results obtained in the present study showing an association between specific LTA and SOD1/SOD2 genotypes and the development of focal migraine-related visible WMHs." (PMID 36430258, 2022).
Tremor (8 papers, 2010 to 2025). An unintentional, oscillating to-and-fro muscle movement about a joint axis. "SOD1 + HFD had a significant (p = 0.0052) earlier onset of tremor (median onset = 91 days) compared to SOD1 + ND (median onset = 98 days), loss of normalized grip strength and lower latency to fall on the hangwire test." (PMID 33931719, 2021). "We first assessed body weight, forelimb grip strength, hindlimb tremor and splay to determine disease progression in the SOD1-G93A animals in our hands." (PMID 40600271, 2025). "In G93A SOD1 mice, the onset of ALS symptoms was assessed by the appearance of severe tremor and body weight loss." (PMID 38765264, 2024). "The SOD1Wt/Cpt1a (median onset = 97 days) and SOD1Cpt1a/Cpt1a (median onset = 103 days) had significantly (p = 0.0014) later onset of tremor compared to SOD1 (median onset = 93 days)." (PMID 33931719, 2021). "Interestingly, the SOD1 + P mice (median onset = 89 days) developed tremor significantly earlier (p = <0.0001) compared to the SOD1 + E mice (median onset = 106.5 days), indicating that etomoxir delayed disease onset." (PMID 33931719, 2021). "SOD1 G93A mice receiving corticosterone (SOD1 + CORT) had significant (p = 0.03) earlier onset of tremor (median onset = 79 days) compared to SOD1 + V (median onset = 87 days), higher neurological score, decreased latency to fall and decreased normalized grip strength." (PMID 33931719, 2021). "Even by taking into account the same type of parameters, such as tremor onset, contradictory data have been reported on sex differences; some authors reported a delayed clinical manifestation in female SOD1 mice, while no sex-related differences exist for others." (PMID 36613534, 2022). "In the SOD-1 (G93A)PS line, tremor was inconsistent and not present in all mice." (PMID 21102999, 2010).
vitamin D deficiency (8 papers, 2020 to 2025). A nutritional condition produced by a deficiency of VITAMIN D in the diet, insufficient production of vitamin D in the skin, inadequate absorption of vitamin D from the diet, or abnormal conversion of vitamin D to its bioactive metabolites. "In an amyloid presenilin model, 13 weeks of vitamin D deficiency exacerbated the ROS production in this model by downregulating superoxide dismutase 1 (SOD1), glutathione peroxidase 4 and enhanced the expression of IL-1β, IL-6 and TNFα, along with increased Aβ production and Tau phosphorylation." (PMID 36297037, 2022).
Atrophy (7 papers, 2014 to 2026). Any weakening or degeneration, especially through lack of use. "Models with a muscle-restricted distribution of SOD1 G93A mutation also show progressive muscular atrophy, mitochondrial dysfunction, and reduced muscle strength and the atrophic muscles of these mice up-regulate autophagy genes, including LC3." (PMID 29653597, 2018). "Our experiments on a limb-onset model of SOD1 demonstrated that iron accumulation in the cervical spinal cord appeared at the time of symptom onset and thus preceded atrophy." (PMID 29379040, 2018). "It has been reported that Cu, Zn-SOD1-knockout (Sod1−/−) leads to aggravation of oxidative stress status resulting in various aging phenotypes including skin and muscle atrophy, fatty liver deposits, and macular degeneration." (PMID 25036096, 2014). "The brain weight of seven patients (patients 4, 5 and 6 with pTDP-43-ir NCI, 8 with FUS-ir NCI, and 9–11 with SOD1-ir NCI) was >1000 g, and their pons and midbrain showed mild to moderate atrophy." (PMID 27716404, 2016).
Cachexia (7 papers, 2017 to 2025). Severe weight loss, wasting of muscle, loss of appetite, and general debility related to a chronic disease. "In summary, these results show that pridopidine can modify the disease phenotype of ALS‐associated cachexia and motor deficits in a SOD1 G93A mouse model." (PMID 35080077, 2022). "The insertion of the human SOD1 G93A mutation in transgenic mice progressively produces cachexia, paralysis, and finally, death resulting from the degeneration of motor neurons induced by the toxic gain‐of‐function of SOD1 protein." (PMID 35080077, 2022). "When a cachexia-inducing tumor such as LLC was injected in SOD1 knock out (KO) mice, the cancer-induced muscle loss and dysfunction were not further exacerbated by OS, while a quarter of the mice died earlier than LLC-bearing WT mice." (PMID 33255345, 2020). "Based on these results, elevated oxidative stress may not exacerbate cancer‐related loss of muscle mass and function; however, if cancer cachexia was allowed to further progress, it is possible that loss of Sod1 could exacerbate the phenotype at a later time point." (PMID 32918528, 2020). "Pridopidine‐treated SOD1 G93A mice showed genotype‐specific effects with the prevention of cachexia." (PMID 35080077, 2022). "Moreover, when a cachexia‐inducing tumour such as LLC was injected in SOD1 knock‐out mice, a quarter of the mice died earlier than LLC‐bearing WT mice." (PMID 35611892, 2022). "In cancer-cachexia rats, treatment with formoterol did not significantly modify protein SOD1, SOD2, or catalase levels in either diaphragm or gastrocnemius muscles." (PMID 29255650, 2017). "SOD1 levels were significantly higher in the limb muscle of cancer-cachexia rats than those detected in non-cachexia control animals." (PMID 29255650, 2017). "In the current study, levels of cytosolic SOD1, but not those of SOD2, were significantly greater in the limb muscle of the cancer-cachexia rats than in control animals." (PMID 29255650, 2017).
Glucose intolerance (7 papers, 2017 to 2024). Glucose intolerance (GI) can be defined as dysglycemia that comprises both prediabetes and diabetes. "Conversely, genetic disruption of the SOD1 gene causes glucose intolerance and impairs beta cell function." (PMID 38166541, 2024). "We next investigated the molecular mechanisms underlying, in the one hand, glucose intolerance in SOD1(G93A) ALS mice and, on the other, specific exercise-induced potential restoration of glucose uptake by ALS mouse tissues, including skeletal muscles." (PMID 29104532, 2017). "Genetic disruption of the SOD1 gene causes glucose intolerance and impairs β-cell function." (PMID 36233271, 2022). "All these data concurred with a glucose intolerance in SOD1(G93A) ALS mice and further substantiated a defect in glucose uptake." (PMID 29104532, 2017). "In the present study, we demonstrated that a significant glucose intolerance occurs in SOD1(G93A) ALS mice since the presymptomatic phase of the disease (P70)." (PMID 29104532, 2017). "Sod1 gene disruption has shown to induce glucose intolerance through β cell dysfunction." (PMID 35580081, 2022). "Since glucose intolerance was recorded for the first time in SOD1(G93A) ALS mice, we decided to verify and confirm these results by quantifying glycogen and glucose concentration levels using nuclear magnetic resonance (NMR) in the skeletal muscle of SOD1(G93A) ALS and control mice." (PMID 29104532, 2017). "Using physiological tests and a biophysics approach based on nuclear magnetic resonance (NMR), we unexpectedly found that SOD1(G93A) ALS mice suffered from severe glucose intolerance, which was counteracted by high intensity swimming but not moderate intensity running exercise." (PMID 29104532, 2017).
ischemia reperfusion injury (7 papers, 2012 to 2023). Adverse functional, metabolic, or structural changes in ischemic tissues resulting from the restoration of blood flow to the tissue (reperfusion), including swelling; hemorrhage; necrosis; and damage from free radicals. "Previous studies of stress-related genes showed that SOD1 enzymatic activity increases during oxidative stress, such as that induced by ischemia-reperfusion injury or in optic neuropathies." (PMID 36233171, 2022).
leishmaniasis (7 papers, 2010 to 2024). Infectious disease that is transmitted through the bite of hematophagous female phlebotomine sand flies. "As an illustration, certain cytokines (IL-10 and IL-27) and antioxidative enzymes (SOD1 and HO-1) encourage the establishment of infection and create an intracellular environment for the development of leishmaniasis." (PMID 37507911, 2023). "The replication and initial establishment of L. amazonensis infection after IFN-I treatment is partly dependent on the enzyme superoxide dismutase 1 (SOD1), which reduces the oxidative stress that is unfavorable to Leishmania and may promote the development and affect the outcome of leishmaniasis." (PMID 31998662, 2019).
liver failure (7 papers, 2018 to 2024). A liver disease characterized by the liver losing or has lost all of its function. "The results revealed that the DKO mice spontaneously develop severe liver failure accompanied by increased levels of oxidative stress and the ER stress occurs early in life, suggesting that Sod1 and Prdx4 have protective roles against liver failure." (PMID 30050648, 2018).
renal fibrosis (7 papers, 2020 to 2025). A final common manifestation of a wide variety of chronic kidney diseases characterized by glomerulosclerosis and tubulointerstitial fibrosis. "And the activation of Nrf2/ARE pathway can promote the expression of a range of downstream antioxidant enzymes, including heme oxygenase 1 (HO-1) and superoxide dismutase 1 (SOD-1), thereby reducing ROS level and resisting the renal fibrosis injury induced by oxidative stress." (PMID 33519483, 2020).
thyroid cancer (7 papers, 2012 to 2024). "In contrast, the gene expression pattern differed in SOD1-ALS, where most DEGs were associated with the thyroid cancer, glycosphingolipid/proteoglycan biosynthesis, long term depression and carbon metabolism pathways, suggesting the impact of neurometabolic defects on SOD1-ALS pathology." (PMID 32967368, 2020). "The average Log2 median-centered intensity-normalized SOD2 expression in the normal thyroid is markedly lower, −0.34, than that of SOD1 and SOD3 but different from these two because SOD2 expression gradually increases, correlating with the malignancy of thyroid cancer." (PMID 29478325, 2019).
thyroid disorders (7 papers, 2015 to 2025). "Both SOD1 and SOD2, which catalyze the dismutation of superoxide radicals into less reactive hydrogen peroxide and oxygen, were significantly higher expressed in the thyroid lesions compared to TN." (PMID 32603365, 2020).
vascular dementia (7 papers, 2012 to 2025). A degenerative vascular disorder affecting the brain. "Oxidative stress is a primary contributor to brain damage in vascular dementia, and Superoxide Dismutase (SOD1) plays a crucial role in detoxifying reactive oxygen species (ROS)." (PMID 41032496, 2025).
brain tumor (6 papers, 2020 to 2024). "Single nucleotide polymorphisms of OS-responsive genes, such as CAT, SOD1, SOD2, SOD3, GPx1, NOS3, and PON1 have been found in adult brain tumor studies." (PMID 36307808, 2022). "A higher concentration of SOD1 in plasma and erythrocytes in brain tumor patients indicates higher OS." (PMID 36307808, 2022).
esophageal cancer (6 papers, 2019 to 2025). A primary or metastatic malignant neoplasm involving the esophagus. "Scientists discovered that CAFs can regulate the expression of superoxide dismutase 1 (SOD1) in esophageal cancer through CXCL1." (PMID 38455762, 2024).
experimental autoimmune encephalomyelitis (6 papers, 2018 to 2025). An autoimmune demyelinating disease of the central nervous system that is produced experimentally in animals by the injection of homogenized brain or spinal cord in Freund's adjuvant. "Genes highly expressed in adult homeostasis microglia and proinflammation-related genes significantly affected in experimental autoimmune encephalomyelitis, APP/PS1, and SOD1-mutant mouse brains were selected for analysis." (PMID 36720919, 2023).
fibrosarcoma (6 papers, 2006 to 2025). A malignant mesenchymal fibroblastic neoplasm affecting the soft tissue and bone. "The relative mRNA expression levels of selenoprotein W (SELENOW), SEPP1, masculoaponeurotic fibrosarcoma K (MafK), CAT, SOD1, SOD2, and NAD (P)H: quinone oxidoreductase 1 (NQO1) genes in TN + SeNPs-AOS group were higher than TN group (p < 0.05)." (PMID 38001826, 2023).
gestational diabetes (6 papers, 2016 to 2025). Carbohydrate intolerance first diagnosed during pregnancy. "Interestingly, the levels of SOD1 and SOD in the placenta of mothers with gestational diabetes exhibit inconsistencies." (PMID 40735644, 2025).